IL4 (interleukin 4)
Diseases named in the same sentence as IL4 in open-access papers (continued):
Sharing a sentence is not in itself a finding about the gene and the disease.
infection (continued). "A significant difference also was observed between the subgroups (i.e., distinct Leishmania species) analyzed: higher levels of IL-4 (P = 0.0132), IL-10 (P = 0.0085), and IL-17 (P = 0.0042) were detected in patients with infections caused by L. guyanensis than those infected with L. amazonensis." (PMID 25295285, 2014). "We found that, whilst increasing in number, the IL-4gfp+CD4+ Th2 cells became conditioned towards a functionally hypo-responsive phenotype as infection progressed denoted by a progressive loss in their intrinsic ability to produce the cytokines IL-4, IL-5 and IL-2." (PMID 23516361, 2013). "In addition, neonatal BALB/c mice treated with anti-IL-4 or BALB/c IL-4 gene knockout mice were more susceptible to infection than the appropriate control mice." (PMID 22685452, 2012). "Moreover, similar to IL-4 KO mice, neutralization of IL-13 in female p55/p75 KO mice rendered them susceptible to infection and administration of recombinant IL-13 to male p55/p75 KO animals restored parasite expulsion." (PMID 23053395, 2012). "So to understand the interplay between the disease healing inflammatory cytokines IFN-γ, and IL-12 and disease associated cytokines IL-10 and IL-4, we sought to investigate Ag-specific in vitro production of cytokines before and after challenge infection in both STP and LTP studies." (PMID 21311597, 2011). "Th2-associated cytokines, such as IL-4 and IL-10, appear relatively late after infection and may limit immune pathology." (PMID 21957440, 2011). "PCA 2 was made up of the cytokines IL-4 and IL-5 (Th2 cytokines) as well as some antibodies (anti-cercariae/IgM and IgG2 and anti-egg IgM previously associated with both exposure to and protection against infection)." (PMID 21039611, 2010). "for example, IL10 helps to control excessive T helper 1 and CD8+ T cell responses that contribute to the immunopathology associated with infection; it also prevents the overproduction of IL4, IL5, and IL13, which can lead to severe fibrosis during the T helper 2 response." (PMID 20398313, 2010). "This analysis showed a clear difference in levels of parasite-specific antibodies and levels of the Th2 cytokines (IL-4 and IL-5), both of which were significantly higher in older egg-negative people suggesting that these were associated with resistance to infection/re-infection." (PMID 21039611, 2010). "Also, the differential production of IL-12 and IL-4 correlated with control of infection, suggesting the identification of associates of reduced parasite burden after immunization." (PMID 19503834, 2009). "falciparum -IgG1 and -IgG3 in secondary infection, whereas IL4-590 C allele might participated in the regulation of anti-P." (PMID 20003246, 2009). "However, infection of IL-4–deficient C57BL/6 mice leads to full parasite development and patency, indicating that a Th2 response is the key determinant of resistance in these non-permissive mice." (PMID 18446236, 2008). "The findings support the hypothesis that elevated IL-4 production is generally associated with infection, but that TB disease is associated with a relatively increased expression of IL-4 compared to IFN-γ and IL-4δ2." (PMID 18231607, 2008). "However, studies in IL-4–deficient mice, and IL-4 neutralisation in cytokine-sufficient mice revealed that α-GalCer–induced IL-4 production during infection had only a minor role in impaired parasite control." (PMID 18463695, 2008). "The promotion of a Th2 response by IL-4 has been associated with macrophage activation toward the polyamine and arginase pathways, favoring parasite persistence, as well as with the inhibition of IL-12 production, which would otherwise recruit Th1 cells to the infection site." (PMID 41017914, 2025).
infection (continued). "However, the central dogma of Th1 and Th2 cells and their signature cytokines, INF gamma and IL-4/IL-13 related to resistance or susceptibility to infection is changing toward interconnected pathways in which depending on the disease model, the IL-4 and even the IL-13 can mediate Th1 immunity." (PMID 39119291, 2024). "Thus, our study uncovers the ways of IL-4-dependent cell-cell communication underlying early stage of infection to promote long-term memory, which could be exploited for development of new vaccines with more potency for infectious diseases." (PMID 38413575, 2024). "Differently, the T helper-2 (Th2) response with IL-4 and IL-10 production can result in the inhibition of macrophage activation, with a consequent increase in the intracellular replication of the parasite and, therefore, an increased susceptibility to infection and the development of severe disease." (PMID 37764934, 2023). "Moreover, the anti-inflammatory cytokines IL-4 and IL-10 inhibit the production of pro-inflammatory cytokines, and decreased production of IL-4 and IL-10 may increase susceptibility to infections and lead to PTB." (PMID 35860261, 2022). "Herein, the relative expression fold change values of IL-4 and IL-13 were next to those of IL-23, IL-1β, and IL-22, suggesting that a higher expression of Th2-associated cytokine genes coincided with the increased percentage of Th2 cells after infection with intravenous injection." (PMID 33441700, 2021). "Also, since IL-4, IL-10, and IL-1Ra are known to play a detrimental role in enhancing susceptibility to infection, our data indicate that alteration of the balance between protective and regulatory cytokines plays a pivotal role in the establishment of cytokine responses in filarial-TBL coinfection." (PMID 32373129, 2020). "The low level of Th1 and Th2 cytokines IL-12 and Il-4 at the resolving phase of infection in the surviving mice vaccinated with adjuvant combination indicated a lower degree of inflammation, consistent with the lowest weight loss in this group at the peak of infection." (PMID 33603732, 2020). "Therefore, NLRP3 deficiency influences expression of IL-4 and Ym1 in the lung during infection with N. brasiliensis and may control release of Ym1 by alveolar Mφs in the airways." (PMID 31586037, 2019). "Furthermore, early in the infection, components of mosquito saliva and local tissue damage at the site of infection cause neutrophils, basophils and mast cells to elicit a Th2 cytokine response with predominant production of IL-4." (PMID 29020083, 2017). "Thus, comparing yellow cattle and water buffalo demonstrated that downregulation of IL4 is associated with worm expulsion and suggests that the immune response may help sustain infection." (PMID 29253882, 2017). "(CSC, ESC) were evaluated to choose the promising antigen that could be used in early diagnosis of strongyle infection along with the immunoassay that incorporated the measuring of Th1 (TNF-α) and Th2 (IL-4) cytokines to be used as a diagnostic tool refers to the stage of infection." (PMID 28717322, 2017). "Both IL-4 and IL-13 are important in host defense against T. spiralis, likely with different regulatory pathways, where NK cell derived IL-13 may cause some of the pathology associated with infection." (PMID 27267469, 2016). "Thus, demonstrating that IL-4 potently suppresses Th1 and Th17 cell immunity further emphasized that AD skin is fundamentally more susceptible to cutaneous colonization and infection than normal or psoriasis skin." (PMID 26217343, 2015). "These parasites bias the immune response toward Th2 and/or a regulatory environment associated with high levels of IL-4, IL-13, IL-9, IL-5, and IL-10; also, infection with helminths compromises immunity to other unrelated infections and may also affect the efficacy of vaccines." (PMID 26090422, 2015).
infection (continued). "In BALB/c mice, susceptibility to infection with the intracellular parasite Leishmania major is driven largely by the development of T helper 2 (Th2) responses and the production of interleukin (IL)-4 and IL-13, which share a common receptor subunit, the IL-4 receptor alpha chain (IL-4Rα)." (PMID 24204259, 2013). "Moreover, susceptible IL-4 KO mice treated with TNF-α are able to clear infection." (PMID 23053395, 2012). "Even with the similarity to the levels of the untreated control group (which only increased MIF after infection), stimulation with Strongyloides antigens appears to favor the secretion profile of IL‐4, IL‐6, and MIF in some conditions." (PMID 41399974, 2026). "Phenotypicprofiling showed that infection reduced IL-4 expression in both MOsubsets, while Ly6Clow MOs from ST2–/– mice also exhibited decreased IL-17 levels." (PMID 41365681, 2026). "During the early stages of infection, F. hepatica induces a mixed Th1/Th2 response characterized by up‐regulating IL‐4, IL‐10, and TGF‐b." (PMID 41503693, 2026). "In severe infection, mRNAs of IL‐4, IL‐5, IL‐6, IL‐10 and IL‐13 highly expressed compared to the non‐infected control, but the interferon‐ (INF)‐γ expression remained unaltered." (PMID 41503693, 2026). "Functional analysis showed that LAG3-expressing CD4+CD44+ T cells secreted elevated levels of interleukin-4 (IL-4) and IL-10 at 2 and 4 weeks post-infection." (PMID 41680821, 2026). "Infection with the hybrid parasite resulted in higher IL-4 production in the skin compared to the control group." (PMID 41017914, 2025). "As the infection advances, the Th2 response is amplified, accompanied by the suppression of Th1, which allows for a prolonged infection potentially dependent on IL4." (PMID 41150396, 2025). "Higher IL-4 and IL-10 levels seen at later time points following infection are likely correlated with this type of Th2 bias." (PMID 40704892, 2025). "Infection of the strain B10.O20 resulted in 15-350× increase of splenocytes’ production of IFNγ IL-2, IL-4, IL-6, IL-10 and IL-17." (PMID 41164189, 2025). "In subtype C, we found that the changes in the biomarker profiles post infection compared to pre-infection were due to increases in TNFα, IL-10, IL-6, IL-13, IL-5, IFNγ, IL-12, IL-4, ITAC, IL-17α, and IL-23." (PMID 40862133, 2025). "High-dose infection with all the strains elicited significant increases in GM-CSF, IL-1β, IL-2, IL-4, IL-5, IL-6, and IL-12p70 when compared with the PBS control." (PMID 40333117, 2025). "Consistent with changes in DNA methylation levels, expressions of Il4, Il13, Cd200, and Il1rl1 were highest on the first day of infection and gradually decreased over time." (PMID 40170749, 2025). "In the K18-hACE2-tg mouse model, a cytokine storm including IL-6, IL-17, and IL-4 occurred in the lungs following SARS-CoV-2 Wuhan infection." (PMID 40270072, 2025). "This limitation is particularly important when interpreting immune markers like IL-4 and eosinophils, as their levels can fluctuate during different stages of infection." (PMID 40526709, 2025). "We didnot observe any changes in IL-2, IL-4, or IL-10 levels resulting fromthe infection; however, ravuconazole-treated mice presented higherlevels of IL-4, and combination therapy significantly increased theIL-4 and IL-10 compared to untreated infected mice." (PMID 40488037, 2025). "Systemically, MCP-1 recruits monocytes and dendritic cells to infection sites, while IL-4/IL-13 drives B-cell class switching, and IL-10/TGF-β modulate inflammation to prevent tissue damage." (PMID 40668875, 2025). "In BALB/c and C57BL/6 mice, IFN-γ and IL-4 are increased in the infected group compared to naïve throughout the acute infection." (PMID 40356908, 2025). "Whilst initial infection stimulates a mixed Th1/Th2 cytokine response, parasite egg production from 4-5 weeks post-infection promotes a dominant type 2 inflammatory response with high levels of IL-4, IL-5 and IL-13 (weeks 6–8)." (PMID 41296814, 2025).
infection (continued). "Infected tissues exhibited similar or lower IL-4 levels compared to uninfected controls at both 4 and 24 h post-infection." (PMID 41450943, 2025). "Gene expression of pro-inflammatory cytokines IL-1β, IL-2, IL-4, and IL-6, as well as IFNγ was significantly upregulated in nasal turbinates in response to infection with all VOCs, compared to mock-infected hamster tissues." (PMID 40295859, 2025). "In infection with L. (V.)guyanensis, higher production of the cytokine IL-4 was observed both in the skin and in the draining lymph nodes compared to the uninfected control group." (PMID 41017914, 2025). "The resulting type 1 IFN response, together with IL-12, promotes Th1 differentiation and IFN-γ production by cytotoxic T cells, while IL-4 primes Th2 differentiation and B cell activation to the site of infection." (PMID 41435987, 2025). "To investigate the infection efficiency and expression levels of IL-4, IL-10, and IL-13 in modified MSCs, we examined their fluorescence and secretion levels." (PMID 40038782, 2025). "Immunological results of the present study showed that the infection induced a highly significant rise in the levels of both IL-2 and IL-4 compared to normal uninfected control in both the intestinal and muscular phases." (PMID 40679976, 2025). "Th2- and eosinophil-expressed IL-4 increased sharply at late-phase time points after infection, peaking at 42 days and remaining elevated up to 70 days after infection, overwhelming local production of IL-17 and IFNγ." (PMID 41294879, 2025). "In murine models, eosinophil accumulation is driven by cytokines such as IL-13, which promotes recruitment to the infection site, and IL-4, which enhances IgE production." (PMID 41479896, 2025). "This response is characterized by the production of cytokines such as IL-4, IL-5, IL-6, IL-10, and IL-13, which deactivate infected macrophages and allow parasite dissemination at infection sites and internal organs." (PMID 40391226, 2025). "Concentrations of IL-4 were higher in the breakthrough infection mice compared to the mock-challenged controls at 7 DPC, but still significantly lower than the primary infection mice." (PMID 41190814, 2025). "And the ITA infection group showed more significant upregulation of cytokines (IL-4, IL-10, TNF-α, IFN-γ), histopathological damage to lungs, and higher bacterial load and mortality than the IN and ITI groups." (PMID 40723822, 2025). "Probiotics also have a negative effect on biofilm formation and modulate the host cell immune response to infection by influencing the balance of pro- and anti-inflammatory cytokines (e.g., IL-8, IL-10, TNFα, IL-1β, and IL-4)." (PMID 41009849, 2025). "We analyzed levels of cytokines at the site of infection including IFNγ, IL-10, IL-17, IL-4, and IL-13 by quantitative real-time PCR." (PMID 40655011, 2025). "C57BL/6 mice are more resistant to this infection than BALB/c and IL-4-deficient (IL4−/−) C57BL/6 mice exhibited increased parasite burdens, heightened IFN-γ and TNF-α production, and a shift from IgG1 to IgG2a antibodies." (PMID 40725240, 2025). "The type 2 cytokines IL-4 and IL-13 are critical for the control of primary and challenge infections with H. p. bakeri." (PMID 39910093, 2025). "The infection activated the upregulation of cytokine expression (il4/13a: 2.6-fold; il4/13b: 5.4-fold), and downregulation of il1b and il8." (PMID 40821846, 2025). "The shift toward Mφ2, often seen during infection, relies on an ERα-mediated pathway that promotes interleukin-4 (IL-4) secretion, enhancing Mφ2 differentiation while inhibiting NFκB signaling and nitric oxide production, thus suppressing Mφ1 activity." (PMID 39791759, 2025). "Arg1 expression was dependent on IL-4, which was present in the lung at low levels before infection." (PMID 40854598, 2025). "In the rCsCP3 immunized group, IFN-γ, IL-2, and IL-10 were elevated from the first week post-infection (P < 0.01), with IL-4 levels increasing in the second week." (PMID 40248698, 2025).
infection (continued). "As the infection or inflammation progresses, fetal leukocytes begin to infiltrate, resulting in elevated concentrations of pro-inflammatory cytokines such as IL-1β, IL-4, IL-6, and IL-8." (PMID 40640885, 2025). "Here we show that colonic lamina propria ILC2s expand in response to CR infection and secrete IL-4, IL-5 and IL- 13, which are involved in maintenance of the intestinal barrier function, tissue repair and mucus secretion." (PMID 40591723, 2025). "In the rCsCP2 immunized group, IL-2 and IL-4 levels rose from the second and fourth weeks post-infection, while IFN-γ levels decreased noticeably, and IL-10 expression remained unchanged compared to controls." (PMID 40248698, 2025). "Overexpressed in keratinocytes of AD patients, IL-33 is rapidly released in response to injury or infection, triggering Th2 polarization by activating immune cells such as mast cells and group 2 innate lymphoid cells (ILC2s) to produce IL-4, IL-5, and IL-13." (PMID 41020006, 2025). "As a result, the adaptive cellular response to BRSV infection is suppressed by early IL-4 production, at least in the initial stages of the infection." (PMID 40261882, 2025). "In the CsCP2-immunized group, IgG1/IgG2a levels gradually increased, and IL-2 and IL-4 expression significantly surpassed that of the control group at four weeks post-infection." (PMID 40248698, 2025). "Our data revealed that the levels of most inflammatory cytokines, such as IL-8, IL-1β, IL-4, IL-6, and IL-2, etc., persistently increased with time during CV-A10 infection." (PMID 41165313, 2025). "- Predominant granulocyte at infection site (~2.5 h).- Adhere to parasite via Fc–Fc interaction with IgG.- Contribute to a Th2 cytokine secretion (IL-4, IL-13)." (PMID 41479896, 2025). "On the other hand, susceptibility to Leishmania is generally supported by the early production of IL-4, which promotes the development of lesions during the early stages of infection, and this cytokine is able to downregulate IL-12 production." (PMID 40299671, 2025). "To assess the immunomodulatory effects of the Lectin-Fc(IgG) treatments during C. auris infection, we measured the levels of IFN-γ, IL-4, and IL-17 in the spleen, kidney, and liver at 7 days post-infection." (PMID 41159718, 2025). "Infection induced a significant increase in IL-4 levels only after 24 h of evaluation (24 h: 45.56 ± 4.987 pg/mL) when compared to RPMI group (24 h: 16.36 ± 2.089 pg/mL; 48 h: 29.18 ± 4.988 pg/mL)." (PMID 40299671, 2025). "It is noteworthy that, 48 h post-infection, there was a sharp decrease in IL-4 levels, an increase in IL-10, and a reduction in IL-12 induced by CM, highlighting, therefore, the ability of this molecule to balance the Th1 and Th2 responses." (PMID 40299671, 2025). "Even though only 5 of the 240 individuals in this study had detectable IL-4 in semen, all had Sh infection with high burden of infection, as measured by concentration of seminal eggs." (PMID 39250522, 2024). "In this regard, basophils are also cells of the innate immune system that migrate to inflammatory sites during allergic inflammation and infection that triggers the production of IL-4, which stimulates the proliferation of B and T cells." (PMID 38807995, 2024). "Although representing a relatively small frequency of all cells, a large fraction (>80%) of eosinophils produced IL-4 throughout the course of infection despite the clear Th1-type cytokine environment." (PMID 38814732, 2024). "Splenic eosinophils exhibited increased MFI of IL-4 on d2 post infection as detected by FACS, further confirming the expression of IL-4 by eosinophils upon L.m." (PMID 38413575, 2024). "IL-4 promotes the type 2 immune response, which is detrimental to host protection during infection in mice (13, –, 17)." (PMID 39287443, 2024).